COMT (catechol-O-methyltransferase)
Diseases named in the same sentence as COMT in open-access papers (continued):
Sharing a sentence is not in itself a finding about the gene and the disease.
schizophrenia (continued). "The gene for catechol-O-methyltransferase (COMT) that metabolizes released dopamine is one of the susceptibility genes located in chromosome 22q11.2 and has been repeatedly reported to be involved in schizophrenia." (PMID 19424500, 2009). "To clarify the impact of COMT genotype at great length, we also conducted the confirmatory analysis to drop the Met/Met subjects from the analyses (patients with schizophrenia: Val/Met: N = 21, Val/Val: N = 20; Healthy controls: Val/Met: N = 25, Val/Val: N = 30)." (PMID 19424500, 2009). "Previous studies showed that the COMT Met genotype is associated with greater improvement of memory performance and negative symptoms in patients with schizophrenia treated with antipsychotic drugs." (PMID 19424500, 2009). "Increased COMT expression in schizophrenia patients may be responsible for disrupted dopamine-glutamate interactions and glial abnormalities." (PMID 19445674, 2009). "However, variances in [deoxy-Hb] were too small to detect the impact of the COMT genotype in patients with schizophrenia in this study." (PMID 19424500, 2009). "In contrast, the inverted-U curve may be shifted in schizophrenia, possibly resulting in a larger effect of the COMT genotype on the prefrontal cortical function as measured by NIRS." (PMID 19424500, 2009). "Finally, our adhesion studies and findings have brought at least three promising schizophrenia susceptibility genes–NRG1, COMT, and Akt1–together in a coherent, biologically plausible framework." (PMID 18159252, 2007). "COMT genotype was significantly associated with schizophrenia (deficit and nondeficit combined; age- and sex-adjusted Odds Ratio = 3.24, p = 0.004 by genotype test), with Val allele frequencies of 0.68 and 0.43, in cases and controls, respectively." (PMID 17173666, 2006). "It has been postulated that schizophrenics may show a decrease in COMT expression, paralleling the 22q11 haploinsufficiency seen in individuals with VCFS, who are at greater risk of developing schizophrenia." (PMID 16483362, 2006). "Recent focus has thus shifted to haplotype analysis of the COMT gene in schizophrenia." (PMID 16483362, 2006). "In this report we did not observe a significant difference between deficit and nondeficit schizophrenia subtypes in either COMT allele or genotype frequencies." (PMID 17173666, 2006). "Based on the concept that COMT regulates dopamine metabolism, epigenetic regulation of COMT influences not only gene expression and enzyme activity but neurotransmitter metabolism and alters dopamine signaling, key features in schizophrenia and cognitive dysfunction." (PMID 41234420, 2025). "Analyzing the combined effect of the sex dimorphism of Dys on prefrontal working memory through the interaction with COMT during estrogenic periods during lifespan may reveal schizophrenia-related pathophysiological processes trackable across age stages and sexes." (PMID 38532008, 2024). "Nicotine intake (smoking) was found to enhance sensory gating in healthy individuals with baseline low rates of P50 suppression (mainly, in carriers of Val/Val variant of COMT rs4680 polymorphism) and in patients with schizophrenia, but not in bipolar disorder." (PMID 35846783, 2022). "COMT might, however, confer a small risk for schizophrenia that is difficult to detect or it may not directly act on the risk for the disease, but modulate the impact of other risk factors such as environmental ones." (PMID 35741850, 2022). "The dopamine hypothesis, the current leading theory of the pathogenesis of schizophrenia, is supported by genetic studies indicating that single nucleotide variations (SNVs) related to dopaminergic transmission, such as DRD2, COMT, DISC1, and PCLO, are associated with a higher risk of schizophrenia." (PMID 34063598, 2021). "The COMT Val108/158Met genotype is related to Akt phosphorylation, and information on functional interactions between COMT and AKt may provide novel insights into the pathogenesis of schizophrenia." (PMID 33315097, 2021).
schizophrenia (continued). "Besides, variation in other genes such as DRD2, which encodes the dopamine receptor DR2, a FOXO6 risk allele, and the catechol-O-methyltransferase (COMT) gene are associated with the severity of negative symptom in patients with schizophrenia." (PMID 34227057, 2021). "Research into the pharmacogenomic influence is however nascent, with most of the focus being on the relationship with cannabis dependence (e.g. CNR1 receptor SNPs which shows no obvious association), or schizophrenia (COMT, DRD2 SNPs showing a stronger correlation)." (PMID 31948424, 2020). "The COMT gene rs165599 SNP does not appear to be a single‐risk factor for schizophrenia." (PMID 30165727, 2018). "Such associations of COMT rs4680 and rs4818 high-activity (G variants), as well as G-G/G-G haplotype, with the lower risk of TRS in females, but not in males, suggest significant, but sex-specific influence of COMT variants on the development of treatment-resistance in patients with schizophrenia." (PMID 30018555, 2018). "Accordingly, we might speculate that determination of the COMT rs4680 and rs4818 genotypes and haplotypes early in the course of treatment might help in the prediction of the treatment-resistance in female patients with schizophrenia." (PMID 30018555, 2018). "As COMT hyperactivity in schizophrenia might result in decreased dopaminergic neurotransmission in the PFC, and consequently to the development of negative and cognitive symptoms of schizophrenia, different COMT inhibitors have been investigated for potential treatment." (PMID 28358316, 2017). "However, initial reports of a significant association between the COMT gene and schizophrenia were not confirmed by later meta-analyses." (PMID 28101524, 2016). "The results showed the top five associated SNPs with CSS of ERBB4, NRG1 and COMT respectively, while none of the SNPs of schizophrenia associated genes COMT, ERBB4 or NRG1 was satisfied the criteria of GWAS significance threshold (Bonferroni correction P < 0.05/498,648, or i.e., ~1.0 × 10−7)." (PMID 26242244, 2015). "Individuals with the Val/Val catechol-O-methyltransferase (COMT, enzyme that deactivates catecholamines) polymorphism [Val(108/158)Met] exhibit higher COMT activity that correlates with lower DA levels in the PFC, and have a slightly higher risk of developing schizophrenia." (PMID 25140130, 2014). "While the specific role of catecholestrogens on G×S interactions of COMT in schizophrenia remains to be investigated, the reduction of COMT activity in females may explain the lower susceptibility of this gender for the phenotypic effects of the Val variant on PFC function." (PMID 24639636, 2014). "Nevertheless, multiple lines of evidence indicate that high-activity COMT variants is robustly associated with a greater severity of negative and cognitive symptoms in schizophrenia patients, as well as specific endophenotypic impairments related to functional deficits of the PFC." (PMID 24639636, 2014). "Furthermore, in patients with schizophrenia, an interaction of the COMT Val108/158Met genotype and antipsychotic treatment on cognitive functioning has been reported, Met allele load predicting better cognitive performance, especially in tasks requiring effortful cognitive control." (PMID 23421957, 2013). "This suggests that the COMT gene may not contribute to the risk for schizophrenia among the Mexican population." (PMID 23184041, 2013). "In addition, a recent study that simultaneously used healthy subjects and patients with schizophrenia demonstrated that the effect of the COMT Val158Met genotype on the cognitive function of healthy controls was opposite to the effect in patients with schizophrenia." (PMID 24282499, 2013). "However, as for many genes in the schizophrenia literature meta-analytic review of gene association investigations implicating COMT have shown that the findings of association do not hold up when comparing across studies." (PMID 23805071, 2013).
schizophrenia (continued). "However, the original reason for COMT genotyping in these patients was to study association between this genotype and the diagnosis of schizophrenia rather than violence." (PMID 22905266, 2012). "Therefore, we investigated the impact of four SNPs, which were previously linked to sensorimotor gating and schizophrenia, on PPI in a new and independent sample of healthy human volunteers: The linked 5-HT2AR T102C/A-1438 G, the COMT Val158Met, and the NRG-1 Arg38Gln polymorphisms." (PMID 19545856, 2009). "Using a 52-channel NIRS with a wide coverage over the prefrontal cortical surface area, we showed that the prefrontal hemodynamic response during a verbal fluency task was significantly associated with COMT genotype in patients with schizophrenia, but not in healthy controls." (PMID 19424500, 2009). "These suggest that the COMT Met allele might be one of the influential factors in the evolution of the human hierarchical PFC and one of the protective factors in the development of prefrontal cognitive dysfunction in schizophrenia." (PMID 19424500, 2009). "Furthermore, gene association studies of COMT in schizophrenia do not ubiquitously support an aetiological role for variants within the gene." (PMID 16483362, 2006). "Evidence from family-based and case-control studies generally suggest that COMT Val158Met polymorphism might be associated with schizophrenia with some negative reports." (PMID 17173666, 2006). "Focusing on neurotransmitter regulation within the prefrontal cortex’s dopaminergic circuits, this study emphasizes the role of genes like COMT, PRODH, and DRD in shaping executive functions and influencing conditions such as ADHD and schizophrenia." (PMID 38392589, 2024). "According to the results of our investigation, the prognostic level is closely correlated with the variations in the expression of the schizophrenia-related genes HTR2A, COMT, and PRODH in various malignancies." (PMID 37564635, 2023). "In various cancer types, schizophrenia-related genes (HTR2A, COMT, and PRODH) have different expression patterns, and the direction of down-regulation varies." (PMID 37564635, 2023). "Studies of mouse models and 22q11DS patients have provided evidence supporting the idea of an epistatic interaction between COMT and PRODH as they both functionally converge on the dopaminergic system and give rise to a hyper-dopaminergic state that may predispose to psychosis and schizophrenia." (PMID 35457231, 2022). "For instance, the hypomethylation of promoter region of catechol-O-methyltransferase (COMT), the gene from dopaminergic pathway, has been revealed in frontal lobe in schizophrenia." (PMID 34366776, 2021). "A neuroimaging-based study done in 2019 included 55 first-episode schizophrenia (FES) cases and 53 healthy controls and genotyped them to assess how COMT contributes genetically to dorsolateral prefrontal cortex (DLPFC) changes in FES." (PMID 34725583, 2021). "Some concordance for methylation status has been observed between blood and brain in relation to schizophrenia candidate genes, including RELN and COMT." (PMID 32764320, 2020). "In terms of neurocognitive-genetic investigations, catechol-O-methyltransferase (COMT) and brain-derived neurotrophic factor (BDNF) are the two most studied candidate genes especially in patients with schizophrenia." (PMID 30349492, 2018). "In male patients with schizophrenia, in the TRS group, COMT rs4818 (χ2 = 1.333; df = 1; p = 0.248) and COMT rs4680 (χ2 = 0.929; df = 1; p = 0.335) genotypes distributions did not deviate from HWE." (PMID 30018555, 2018). "Previous research has indicated that variation in genes encoding catechol‐O‐methyltransferase (COMT) and dopamine receptor D2 (DRD2) may influence cognitive function and that this may confer vulnerability to the development of mental health disorders such as schizophrenia." (PMID 28523234, 2017).
schizophrenia (continued). "Genes such as COMT and REELIN, as well as a few others in the dopaminergic, serotonergic and GABAergic pathways, have also shown differential methylation profiles in schizophrenia samples." (PMID 28117656, 2016). "Therefore, given their differing mechanisms of action and complementary effects on homocysteine production, both the MTHFR 677T and COMT Val alleles may potentially increase the risk for CVD, which makes both pertinent to schizophrenia and AAP-associated metabolic risks." (PMID 27336047, 2015). "In addition, our group reported gene-specific methylation differences related to COMT that suggest that COMT promoter region methylation is largely influenced by COMT genotype and that physical activity has a significant role in epigenetic modulation of COMT in the schizophrenia population." (PMID 27336047, 2015). "However, multiple lines of evidence indicate that the high-activity COMT Val allele is associated with greater severity of negative and cognitive symptoms in schizophrenia, as well as specific endophenotypic impairments related to prefrontal deficits such as schizotypal traits." (PMID 25722988, 2015). "After adjusting for age and PMI, DTNBP1, COMT and DRD2 were found to be differentially methylated between the two schizophrenia subgroups." (PMID 24399042, 2014). "The results revealed a significant correlation between membrane-bound COMT (MB-COMT) promoter hypo-methylation (especially at SP1 binding sites) and over-expression of the MB-COMT gene product in schizophrenia and bipolar disorder." (PMID 21358990, 2010). "Studies in schizophrenia show that RELN hypermethylation reduces reelin expression and disrupts synaptic plasticity and neuronal migration; COMT methylation alters dopamine metabolism; and BDNF methylation is associated with cognitive impairment and negative symptoms." (PMID 41234420, 2025). "DNA methylation changes at COMT and KCNAB3 may be one of the pathways involved in the pathophysiology of schizophrenia at least in a subgroup of patients although this needs further research." (PMID 38503926, 2024). "In this study, we first investigated the effect of increased expression of selected 3 miRNAs on COMT expression in SH-SY5Y cells, which are used as a model for schizophrenia and we observed that higher levels of miR-30a-5p and miR-34a-5p inhibited COMT expression both on mRNA and protein levels." (PMID 38427212, 2024). "Besides schizophrenia, ID, and ASD, COMT function in the context of dopamine regulation is also associated with addiction and depression." (PMID 35590332, 2022). "Furthermore, the risk for schizophrenia conferred by T. gondii was modified by the COMT genotype, with those who had been exposed to the infection showing a different risk compared to that of nonexposed ones depending on the COMT genotype (χ2 for the interaction = 7.28, p-value = 0.007)." (PMID 35741850, 2022). "The study determined the association between COMT rs4680 and rs4818, MAO-B rs1799836 and rs6651806 polymorphisms, the severity of negative symptoms, and physical and social anhedonia in schizophrenia." (PMID 34287249, 2021). "There are no data on the relationship between COMT rs4818 and anhedonia in any population, whereas the MAO-B rs6651806 polymorphism, to the best of our knowledge, has not been investigated in schizophrenia." (PMID 34287249, 2021). "Similarly, COMT is a gene of interest in methylation studies of psychosis because its product, catechol-O-methyltransferase, is involved in the metabolism of dopamine, which is a major driver of positive symptoms and supports the dopamine hypothesis of schizophrenia." (PMID 32764320, 2020). "Variation in the COMT genotype was not strongly related to differences in neural responses between the clinical disorders of schizophrenia and bipolar disorder." (PMID 32950905, 2020).
schizophrenia (continued). "Several genes were validated in APA sperm that were associated with autism spectrum disorder (CACNA1H, CNTNAP2, GRIN1, SHANK2, SHANK3, ZNF804A), schizophrenia (TCF3, ZNF804A), and bipolar disorder (COMT, DRD4, GRIN1, MBP, PRKCZ, SHANK2, TRPM2, ZNF804A), and in APA blastocysts (CACNA1H)." (PMID 32610362, 2020). "Interaction between COMT (elite gene) and NOTCH4 genotypes may predict the treatment response to typical neuroleptics in schizophrenia patients." (PMID 30705251, 2019). "The distribution of the COMT rs4818 and rs4680 genotypes in male patients with schizophrenia subdivided into TRS and non-TRS groups." (PMID 30018555, 2018). "The distribution of COMT rs4680-rs4818 haplotypes in all patients with schizophrenia subdivided into TRS and non-TRS group." (PMID 30018555, 2018). "In summary, dysregulated COMT and SLC6A4 mRNA expressions in schizophrenia provides further evidence supporting that these two genes may implicate in the pathophysiology of schizophrenia." (PMID 30483162, 2018). "Four candidate genes (DRD2, COMT, 5-HTR2A, and SLC6A4) from dopaminergic and serotoninergic pathways have received the most attention in the literature and have been supposed as the promising candidate genes for schizophrenia and treatment response." (PMID 30483162, 2018). "The distribution of the COMT rs4818 and rs4680 genotypes in female patients with schizophrenia subdivided into TRS and non-TRS group." (PMID 30018555, 2018). "Over the range of fasting proline in our schizophrenia sample (87–502 μm), this represents a significant and clinically relevant difference in negative symptoms between COMT genotype groups." (PMID 27622935, 2016). "We therefore tested for effect modification between the Val158Met COMT genotype and fasting peripheral proline on both positive and negative symptoms of schizophrenia." (PMID 27622935, 2016). "We explored the relationship between fasting plasma proline levels and COMT Val158Met genotype on symptoms (positive, negative and total) in schizophrenia patients." (PMID 27622935, 2016). "There was a significant interaction between peripheral proline and COMT on negative symptoms in schizophrenia (P<0.0001, n=95)." (PMID 27622935, 2016). "The data presented in this study demonstrate that fasting peripheral proline and COMT Val158Met genotype, predict negative-symptom severity in schizophrenia." (PMID 27622935, 2016). "The role of COMT in schizophrenia has been extensively studied and it seems that neither genetic variants nor the catalytic activity of the enzyme has great intrinsic influence on schizophrenia risk." (PMID 25722988, 2015). "Eighty-six clinically stabilized schizophrenia patients treated with three months CRT were assessed with the Wisconsin Card Sorting Test, as a measure of executive functions, at enrolment and after CRT treatment, and underwent COMT and 5-HT1A-R genotyping." (PMID 25750798, 2014). "For instance hyper- DNA methylation of RELN, SOX10 [SRY (sex determining region Y)-box 10], FOXP2 (forkhead box P2), and HTR2A as well as hypo- DNA methylation of MB-COMT (membrane-bound catechol-O-methyltransferase) and HTR2A have been reported in schizophrenia." (PMID 25206360, 2014). "Based on this rationale, we hypothesized that 5-HT1A-R rs6295 and COMT rs4680, both involved in regulation of PFC dopaminergic transmission, could affect cognitive remediation outcomes in schizophrenia." (PMID 25750798, 2014). "Animal models also confirm a link between the genetic disturbance of COMT and developmental cannabis such that adolescent THC exposure in transgenic mice lacking endogenous COMT synergistically impacts behaviors relevant to schizophrenia." (PMID 24133461, 2013). "Moreover, it was shown that genetic variation in the catechol-O-methyltransferase (COMT) and the neuregulin-1 (NRG-1) proteins influences PPI in schizophrenia patients and healthy volunteers." (PMID 19545856, 2009).